TCF7L2 (transcription factor 7 like 2)
Diseases named in the same sentence as TCF7L2 in open-access papers (continued):
Sharing a sentence is not in itself a finding about the gene and the disease.
type 2 diabetes (continued). "Both TCF7L2 variants (rs7903146 and rs12255372), HHEX rs1111875, and HNF1A rs7957197 were associated with increased risk of type 2 diabetes." (PMID 27551309, 2016). "Transcription factor 7-like 2 (Tcf7l2) is a unique gene which is a type 2 diabetes candidate gene in the TCF family." (PMID 27782077, 2016). "The rs7903146-T allele in the transcription factor 7-like 2 (TCF7L2) gene has been associated with impaired pancreatic insulin secretion, enhanced liver glucose production, and an increased risk of type 2 diabetes." (PMID 26914832, 2016). "The transcription factor 7-like 2 (TCF7L2) gene is one of those that have been identified as possible determinants of type 2 diabetes mellitus (T2DM)." (PMID 26608632, 2015). "This study aimed to investigate the differences in terms of DNA methylation profile of TCF7L2 promoter gene between type 2 diabetic patients and age- and Body Mass Index (BMI)- matched controls." (PMID 24914535, 2014). "The aim of this study was to compare the epigenetic profile (defined here as the pattern of DNA methylation on TCF7L2 promoter in DNA from peripheral blood) between type 2 diabetic patients and age- and BMI-matched controls." (PMID 24914535, 2014). "In this study, we report the methylation pattern of TCF7L2 promoter from peripheral blood DNA in drug-naïve type 2 diabetic patients and age- and BMI-matched controls." (PMID 24914535, 2014). "Here, we have investigated the role of three type 2 diabetes candidate SNPs well-known in other populations (TCF7L2 rs7903146, KCNJ11 rs5219, PPARγ rs1801282) in more than 1000 Ghanaians." (PMID 24059590, 2013). "The main finding of the present study is a significant interaction found between TCF7L2 genotype and the type of sulfonylurea used in the treatment of the patients with type 2 diabetes." (PMID 23509454, 2013). "Fifth, in a human pancreatic cell line, curcumin increased expression of the transcription factor 7-like 2 (TCF7L2) gene in the Wnt signaling pathway, which is associated with type 2 diabetes." (PMID 24348712, 2013). "TCF7L2 rs7903146, KCNJ11 rs5219, PPARγ rs1801282 and CAPN10 rs3842570, rs3792267, and rs5030952 were typed and associations with type 2 diabetes and phenotypic traits examined." (PMID 24059590, 2013). "TCF7L2 and KCNQ1 were previously considered to be the strongest type 2 diabetes susceptible genes in Caucansians and East Asians, both of which were well replicated in Han Chinese." (PMID 23990951, 2013). "In recent years, it has been widely accepted that transcription factor 7-like 2 (TCF7L2) is associated with type 2 diabetes mellitus (T2DM) in multiple ethnic groups, especially its single nucleotide polymorphisms of rs7903146C/T, rs12255372G/T and rs290487T/C." (PMID 23527206, 2013). "The transcription factor 7-like 2 (TCF7L2) gene, previously reported as TCF-4, has been found to be associated with type 2 diabetes." (PMID 23951231, 2013). "For example, the Type 2 diabetes candidate gene TCF7L2 has a similar methylation pattern along the gene body but there are CpG sites showing unmethylated state in monocytes only (see arrows)." (PMID 22848472, 2012). "The similarity of these loci to those associated with type 2 diabetes, namely, TCF7L2 and CDKAL1, led the authors to propose that GDM and type 2 diabetes were different manifestations of the same genetic entity." (PMID 22577574, 2012). "Among the loci thus tested, the largest effect size for BMI reduction was found at TCF7L2, where the OR for type 2 diabetes was also greatest in Japanese." (PMID 23173044, 2012). "Transcription factor 7-like 2 gene (TCF7L2) rs7903146 to this date remains the strongest and most widely replicated type 2 diabetes susceptibility locus." (PMID 22782288, 2012). "The T allele of transcription factor 7-like 2 gene variant, TCF7L2 rs7903146, increases the risk of type 2 diabetes by 40–50%." (PMID 22782288, 2012).
type 2 diabetes (continued). "Among them, several loci, including TCF7L2, CDKAL1, HHEX, SLC30A8, KCNJ11, CDKN2A/B, IGF2BP2, GCKR, IRS1, and CDC123/CAMK1D, have been shown to be associated with type 2 diabetes in different ethnic groups." (PMID 23029454, 2012). "For example, variants in TCF7L2 predispose to both colon cancer and type 2 diabetes while variants in HNF1B predisposes to type 2 diabetes and prostate cancer." (PMID 22809218, 2012). "Furthermore this SNP was more strongly associated with type 2 diabetes in the combined UKADS/DGP cohorts than most of the currently validated type 2 diabetes risk determinants, with the exception of the TCF7L2 rs7902346 variant, leading us to believe that the association might be genuine." (PMID 22485135, 2012). "For the Type 2 diabetes candidate gene transcription factor 7-like 2 (TCF7L2) on chromosome 10q25.3, the methylation pattern is similar along the gene body but there are certain CpG sites that show unmethylated state in CD14+ monocytes only (see arrows)." (PMID 22848472, 2012). "Variants in HNF1B, UCP2, SLC2A2, IGF2BP2, TCF7L2 and CAPN10 have been shown to predispose to type 2 diabetes and protect against prostate cancer or vice versa." (PMID 22485135, 2012). "Although TCF7L2 has been regarded as one of the major candidate genes for inducing type 2 diabetes, the exact role for this factor in hepatic glucose metabolism has not been well documented." (PMID 23028378, 2012). "Second, polymorphisms in the TCF7L2 gene, one of the LEF/TCF family members that bind and mediate β-catenin activity in the nucleus, are highly associated with the risk of type 2 diabetes." (PMID 22438981, 2012). "Of the previously known genes associated with type 2 diabetes (T2D), variants in GCKR and TCF7L2 were confirmed to be associated with 2 h BG." (PMID 21789219, 2011). "Variants in TCF7L2 and SLC30A8 have previously been associated with type 2 diabetes in our Punjabi populations." (PMID 21949744, 2011). "For the analysis of type 2 diabetes, this study had >80% power to detect the effect of just the TCF7L2 SNP." (PMID 21949744, 2011). "Many genetic variants have been associated with type 2 diabetes, but from a long list of candidate genes only three have unambiguously been associated with the disease: PPARG, KCNJ11 and TCF7L2." (PMID 20161779, 2010). "One such example is the transcription factor 7-like 2 (TCF7L2) gene and the role of SNPs present in that gene in type 2 diabetes." (PMID 21286314, 2010). "SNPs from GIPR, TCF7L2, CRY2, GLIS3 and SLC30A8 were also associated with type 2 diabetes (p = 0.0487∼2.0×10−8)." (PMID 21103350, 2010). "Recently, TCF7L2 variants, including the microsatellite marker DG10S478 and the nearly perfectly linked SNP rs12233372, were identified to associate with type 2 diabetes." (PMID 17109766, 2006). "For type 2 diabetes, the major outcome of these efforts is the identification of TCF7L2." (PMID 40675550, 2025). "Additionally, transcription factor 7‐like 2 (TCF7L2) Gene, a major regulator of insulin production and processing, has been considered a prominent marker in individuals with Type 2 diabetes who have a positive family history of diabetes." (PMID 40820550, 2025). "Type 2 diabetes (T2DM) reflects peripheral insulin resistance, driven by altered receptor signaling and eventual β-cell exhaustion, and a modest genetic predisposition (e.g., TCF7L2 variants increase risk ~1.5-fold)." (PMID 40732323, 2025). "Therefore, any defect in TCF7L2 predisposes the subject to type 2 diabetes mellitus (T2DM)." (PMID 38384655, 2024). "We found that TCF7L2 is preferentially expressed in trunk subcutaneous depots and hypothesize that misregulation of TCF7L2 in abdominal adipocytes could contribute to its reported links to type 2 diabetes." (PMID 39401200, 2024).
type 2 diabetes (continued). "To date, among three out of twenty-two Arab populations, fourteen interactions have been found between the FTO rs9939609, TCF7L2 rs7903146, MC4R rs17782313, and MTHFR rs1801133 polymorphisms and diet or physical activity on obesity and type 2 diabetes outcomes." (PMID 39125399, 2024). "This evidence further strengthens the possibility of a link between TNF-α and TCF7L2 which may play an important role in the co-existence of malaria and type 2 diabetes." (PMID 37215099, 2023). "SIA notably did not detect positive selection at GWAS loci in the TCF7L2 gene associated with type-2 diabetes, the ANKK1 gene implicated in addictive behaviors, and the FTO gene associated with obesity." (PMID 34888675, 2022). "Although expression of TCF7L2 as gene that is most consistently linked to type 2 diabetes in GWAS was not affected in our study, the glucose modulated the expression of important genes and pathways for type 2 diabetes." (PMID 35276968, 2022). "Kaya E.D., Arikoğlu H., Kayiş S.A., Öztürk O., Gönen M.S. Transcriptionfactor 7-like 2 (TCF7L2) gene polymorphisms are strong predictorsof type 2 diabetes among nonobese diabetics in the Turkishpopulation." (PMID 35434484, 2022). "The expression of TCF7L2 has been shown to be reduced in adipose tissue from individuals with type 2 diabetes and in obese mice, indicating that TCF7L2 function in adipose tissue may influence diabetes risk." (PMID 33068125, 2021). "According to the literature study, some genes that are associated with developmental dyslexia, such as ROBO1, DCDC2, DYX1C1, and KIA0319, and some genes that are associated with type 2 diabetes CTNNB1, TCF7L2, and KIF3A had shown some connections with each other." (PMID 34674647, 2021). "Moreover, recently, an interaction between TCF7L2 and obesity in relation to type 2 diabetes has been reported." (PMID 33436000, 2021). "Consistent with previous studies, we find a 50% lower incidence of type 2 diabetes in individuals engaging in high PA vs those who are sedentary, and the risk reduction seemed equally strong in carriers and noncarriers of the TCF7L2 and FTO risk variants." (PMID 32835373, 2020). "For type 2 diabetes, the association with PA did not appear to be modified by either TCF7L2, FTO, or HLA." (PMID 32835373, 2020). "Deregulation of TCF7L2 may be involved in diseases including multiple sclerosis, type II diabetes, stroke, and cancer." (PMID 32843642, 2020). "For example, two genotypes linked with the susceptibility of Type 2 Diabetes Mellitus (T2DM); rs7903146 SNP in the TCF7L2 gene [OMIM: 125853], a heterozygous modifier affecting drug response, and the rs4402960 SNP in IGF2BP2 gene [OMIM: 125853] a heterozygous risk factor modifier." (PMID 31604968, 2019). "Additionally, polymorphisms located in introns in the genomic region that codes for human tcf7l2 exon 3a, segregate with acquisition of type-2 diabetes, and conditional knockdowns of tcf7l2 give rise to mice with phenotypes comparable to diabetic patients." (PMID 31829936, 2019). "Adult-onset, or type II diabetes mellitus (T2DM) has a complex genetic architecture, from hundreds of genes with low penetrance, common susceptibility variants (e.g., TCF7L2), to a set of more than ten genes that, when mutated, can cause a single-gene or Mendelian form of T2DM (e.g., GCK)." (PMID 29458357, 2018). "The genome wide association studies have identified various susceptibility genes, including several type 2 diabetes mellitus (T2DM) such as PPARG, TCF7L2, FTO, CDKN2A/2B, and IRS1 etc. to be associated with the risk of T2DM, though their definite relation with GDM remains to be explored further." (PMID 28083030, 2016). "Earlier studies have shown that variants in TCF7L2 were positively selected, and were associated with BMI and levels of ghrelin and leptin; however, no general enrichment of adaptive variants in type 2 diabetes- and obesity-associated loci have been found." (PMID 25222615, 2014).
type 2 diabetes (continued). "A majority of genes associated with type 2 diabetes from this meta-analysis (ADCY5, CDKAL1, CDKN2A/B, HHEX, IGF2BP2, SLC30A8, TCF7L2 and KCNQ1) are involved in pancreatic beta cell function, while two are implicated in insulin sensitivity (PPARG) and adiposity (FTO)." (PMID 25145545, 2014). "Linagliptin significantly improved hyperglycaemia in patients with type 2 diabetes both with and without the TCF7L2 gene diabetes risk alleles." (PMID 24906949, 2014). "Moreover, 18 obesity and 21 type 2 diabetes candidate genes had CpG sites with differences in adipose tissue DNA methylation in response to exercise (q<0.05), including TCF7L2 (6 CpG sites) and KCNQ1 (10 CpG sites)." (PMID 23825961, 2013). "Still another study, a large meta-analysis of 14 cohorts, investigating fasting glucose levels instead of incident type 2 diabetes, did not detect any interaction between the TCF7L2 risk allele and whole-grain intake on that phenotype." (PMID 22782288, 2012). "Of these loci, only GCK, MTNR1B, DGKB, GCKR, ADCY5 and PROX1 (besides TCF7L2 and SLC30A8) were associated with type 2 diabetes at genome-wide significance levels, with several others (but not all) showing a consistent trend but not meeting the same stringent statistical threshold." (PMID 22984506, 2012). "Collectively, these data suggest a crucial role of TCF7L2 in hepatic glucose metabolism; reduced hepatic expression of nuclear isoforms of this factor might be a critical instigator of hyperglycemia in type 2 diabetes." (PMID 23028378, 2012). "Along this line, a few previous studies in Europeans have shown that some genetic variants acting on insulin secretion (e.g., TCF7L2) have a greater impact on type 2 diabetes in non-obese subjects than in obese subjects." (PMID 23173044, 2012). "For example, the variant with the strongest effect on type 2 diabetes risk, in TCF7L2, has a stronger effect in non-obese cases (odds ratio = 1.53 [0.37–1.71] compared to obese cases (OR = 1.21 [1.09–1.35])." (PMID 22693455, 2012). "The cumulative risk of developing islet autoantibodies by age 10 years was 7% (95% CI: 5–9%) in children carrying the TCF7L2 CT or TCF7L2 CC genotype compared to 12% (95% CI: 10–14%) in children carrying the type 2 diabetes protective TCF7L2 TT genotype (P = 0.015; Pcorrected = 0.18)." (PMID 22558147, 2012). "More recently, a lack of association between a TCF7L2 rs7903146 variant and type 2 diabetes was reported in Arabian Emirates, as well as in an Arab population of Saudi origin, although this was completely inconsistent with previous reports." (PMID 21637413, 2010). "This is exemplified by the discovery of TCF7L2 gene with type 2 diabetes." (PMID 20181263, 2010). "We have shown that TCF7L2 polymorphisms (rs12255372 and rs7903146) that have been consistently associated with type 2 diabetes are not significantly (P > 0.05) associated with any of the inflammatory markers in analyses before treatment with fenofibrate." (PMID 19825152, 2009). "In addition, in the “adherens junction” pathway, one of the strongest FST values was showed by TCF7L2, the gene with largest type 2 diabetes effect size found to date." (PMID 19936260, 2009). "For example the TCF7L2 locus shows remarkable linkage disequilibrium with type-2 diabetes." (PMID 19924301, 2009). "Given the documented reproducibility of the association between TCF7L2 and type 2 diabetes, however, we do not believe that cryptic relatedness has affected the results presented in this manuscript." (PMID 18291022, 2008). "Very recently, lack of association between variants in TCF7L2 and type 2 diabetes has been reported in Pima Indians and Chinese diabetics." (PMID 18655717, 2008). "Recently, a number of studies have reported remarkably strong, replicable associations with complex disease, including the complement factor H (CFH) gene in age-related macular degeneration and the transcription factor 7-like-2 (TCF7L2) gene in type 2 diabetes." (PMID 18335027, 2008).
type 2 diabetes (continued). "Indeed, our previous study of individuals with type 1 diabetes found a higher prevalence of type 2 diabetes-associated TCF7L2 SNPs in those who lacked high-risk HLA haplotypes." (PMID 39670998, 2025). "This aligns with prior research identifying SIRD as the most genetically unique subgroup, exhibiting an insulin resistance molecular signature and lacking associations with the type 2 diabetes locus in the TCF7L2 gene or insulin secretion risk scores, contrary to SIDD and MOD." (PMID 38625583, 2024). "TCF7L2 is a member of the T-cell factor/lymphoid enhancer-binding factor family (TCF/LEF), a protein-coding gene known as one of the most potent risk loci for type 2 diabetes, involved in several fundamental processes including adipogenesis, autophagy, and alternative splicing." (PMID 39050860, 2024). "However, the effect(s) of its elevated or reduced levels on the transcriptional activity of the type 2 diabetes gene, TCF7L2 remains unknown." (PMID 37215099, 2023). "However, the mechanism of TCF7L2 gene function and how its genetic polymorphism influence the susceptibility of type 2 diabetes has not been elucidated." (PMID 35677638, 2022). "Therefore, this study was aimed to determine the association of common SNPs (rs7903146 C/T and rs12255372 G/T) of TCF7L2 with susceptibility of type 2 diabetes in population of Northern region of Pakistan from the Khyber-Pakhtunkhwa province." (PMID 34394276, 2021). "The same also has a more critical link to family history and lineage compared to Type I. Any mutations in proteins such as TCF7L2, ABCC8, GLUT2, and CAPN10 favor the progression of Type 2 diabetes because they could influence the production or mechanism of action of insulin." (PMID 34943006, 2021). "The aim of this study was to investigate the association between PA and incidence of LADA compared with the associations regarding type 2 diabetes, as well as whether these associations are modified by HLA, FTO, or TCF7L2 genotypes and potential underlying mechanisms." (PMID 32835373, 2020). "Similarly, previous interaction findings for type 2 diabetes susceptibility genes, such as TCF7L2, GIPR, CAV2, and HFE, with other dietary factors were not replicated in the EPIC-InterACT study." (PMID 32722593, 2020). "Despite that this association was identified in 2006 and has been readily replicated in populations of different ethnic descent, the mechanism through which TCF7L2 exerts its effect on type 2 diabetes mellitus (T2DM) is still very unclear." (PMID 31312258, 2019). "The association between several Single Nucleotide Polymorphisms (SNPs) within the transcription factor 7-like 2 (TCF7L2) gene and Type 2 Diabetes (T2D) as well as additional T2D-related traits is well established." (PMID 31676834, 2019). "The birth weight-raising maternal alleles at the identified loci (MTNR1B, GCK and TCF7L2) are strongly associated with higher fasting glucose and Type 2 diabetes in non-pregnant adults, and with glycemic traits and gestational diabetes mellitus in pregnant women." (PMID 29309628, 2018). "Mechanisms whereby altered TCF7L2 production and/or function may contribute to the development of type 2 diabetes are not fully understood but likely include a decrease in β-cell mass, impaired insulin processing or release, and impaired incretin signaling in β-cells." (PMID 24324494, 2013). "Our study suggests that dietary fibre intake may modify the association between TCF7L2 rs7903146 and incidence of type 2 diabetes, and that higher fibre intake may associate with protection from type 2 diabetes only among non-risk allele carriers." (PMID 22782288, 2012). "From the point of view of type 2 diabetes, whether intronic TCF7L2 SNPs as the ones discussed in the first section affect local DNA methylation states and consequently splicing in a diet- and environment-dependent fashion, it is to our knowledge a yet unanswered question." (PMID 21286314, 2010).